CST3 (cystatin C)
Diseases named in the same sentence as CST3 in open-access papers (continued):
Sharing a sentence is not in itself a finding about the gene and the disease.
renal dysfunction (continued). "Many studies have been conducted to assess the usefulness of cystatin C in predicting cardiovascular risks and renal dysfunction, and various cutoff values have been suggested in multiple clinical settings." (PMID 32306911, 2020). "Our data indicate a renal dysfunction trend across the quartiles of daytime/nighttime urinary sodium excretion ratio when considering the significantly higher values of cystatin C in Q1 compared with subjects in Q4." (PMID 32645850, 2020). "We found that SCFA treatment, especially butyrate, resulted in lowering the levels of urine ACR and in lowering serum urea, creatinine, and cystatin C levels, markers of the severity of renal dysfunction in DN." (PMID 32831998, 2020). "Both Cystatin C and CD14 were associated with increased risk of renal dysfunction in all three EV sub‐fractions." (PMID 32648717, 2020). "We provide the first data showing that Cystatin C and CD14 in circulating EVs are associated with both renal dysfunction and heart failure in patients presenting with acute dyspnoea." (PMID 32648717, 2020). "They found that at a 95% confidence interval and according to the Moses-Littenberg linear regression model, cystatin C was more interoceptive for indicating renal dysfunction compared to Cr [cystatin C: 3.99 (3.41-4.57) versus Cr: 2.79 (2.12-3.4)]." (PMID 30145854, 2019). "Studies on diabetic patients or healthy subjects have found that serum cystatin C is more sensitive during the early stages of renal dysfunction." (PMID 29394255, 2018). "Renal dysfunction was evaluated either by reduced estimated glomerular filtration rate (eGFR) or the presence of proteinuria or increased cystatin C." (PMID 29930507, 2018). "Serum Cystatin C (sCysC) is a well-recognized marker of early renal dysfunction but few reports evaluate its prognostic cardio-vascular role." (PMID 29615540, 2018). "This suggests that cystatin C-based definition of renal dysfunction indicates a potential better clinical utility than creatinine-based formula for predicting poor coronary collaterals in type 2 diabetic patients with stable coronary artery disease." (PMID 29422093, 2018). "And these two measures of renal dysfunction remained as independent predictors after adjusting for all confounding variables (OR 3.16, 95% CI 1.39–7.19 for cystatin C and OR 2.79, 95% CI 1.34–5.83 for proteinuria)." (PMID 29930507, 2018). "Although the serum cystatin C level serves as a valuable tool for early detection of renal dysfunction, it has been reported to be influenced by age, gender, body mass index, smoking status, the C-reactive protein level, nephritis, and hypertension." (PMID 28693441, 2017). "Rather, the association between cystatin C and CAD appeared to be due to the association of renal dysfunction and CAD." (PMID 27218257, 2016). "In further study the more specific attention should be focused on the correlation between cystatin C and even angiopoietin 2, which appeared to be a relevant predictor of renal dysfunction in acute pancreatitis patients." (PMID 28105442, 2016). "Receiver operating characteristic curve analysis illustrated that area under the curve of serum creatinine and cystatin C for detecting renal dysfunction were 0.711 and 0.607, respectively; however, this difference was not significant (P = 0.222)." (PMID 24783172, 2014). "In the case of renal dysfunction (measured Ccr < 80 mL/min/1.73 m2), the AUC (95% CI) for serum creatinine was 0.711 (0.598-0.807) and for serum cystatin C was 0.607 (0.490-0.715)." (PMID 24783172, 2014). "The results of ROC curve analysis demonstrated that the accuracy of serum cystatin C in detection of renal dysfunction (Ccr < 80 mL/min/1.73 m2) was comparable to serum creatinine (AUC = 0.711 vs. 0.607, P = 0.222)." (PMID 24783172, 2014).
renal dysfunction (continued). "Five (20%) of these 25 patients with renal dysfunction had elevated serum creatinine concentrations, whereas 19 (76%) of them had elevated serum cystatin C levels at the time of renal dysfunction (P = 0.032)." (PMID 15774046, 2005). "A creatinine-cystatin C-based sarcopenic index has been proposed as a surrogate marker of muscle status; however, its association with sarcopenia as defined by the EWGSOP2 framework, particularly in the context of renal dysfunction, remains uncertain." (PMID 41827199, 2026). "The serum cystatin C concentration was established to have better sensitivity, specificity, and positive predictive value compared to creatinine in the detection of early stages of renal dysfunction in cancer patients under treatment with cisplatin." (PMID 41010375, 2025). "For young women, markers such as cystatin C and eGFRcysC may be particularly useful in detecting subclinical renal dysfunction, enabling timely preventive interventions." (PMID 41200622, 2025). "Studies venturing into the roles of other biomarkers such as cystatin C, glycated albumin, and advanced glycation end-products, could provide a more comprehensive understanding of the correlation between glycemia and renal dysfunction." (PMID 41190245, 2025). "Therefore, to establish the relationship between S100B levels and renal dysfunction in cirrhotic patients, further study using other renal biomarkers, such as cystatin C, is necessary." (PMID 36766438, 2023). "While early biomarkers of renal dysfunction like creatinine, cystatin c, and urinary beta-2 microglobulin are analyzed in other studies about renal T2* measurements, specific blood tests could not be performed in our study as it was designed retrospectively." (PMID 37065363, 2023). "Furthermore, creatinine-based GFR estimation underestimates existing renal dysfunction compared to a cystatin C-based measurement." (PMID 38132491, 2023). "Cystatin C is involved in the extracellular inhibition of cathepsin and removed from the circulation by tubular cells in the kidneys, which resulted in the identification of this protein as a biomarker for renal dysfunction and cardiovascular disease." (PMID 35087594, 2022). "Therefore, our aim was to assess the biomarkers helpful for the diagnosis of early renal dysfunction by testing for cryoglobulins, RF, complement C3, cystatin C, and creatinine/cystatin C ratio in newly diagnosed HCV-infected patients." (PMID 36466932, 2022). "High serum cystatin C and low creatinine/cystatin C ratio may be early indicators of mild renal dysfunction with normal serum levels of creatinine in HCV-infected individuals." (PMID 36466932, 2022). "It has been reported that cystatin-C concentrations are significantly correlated with IR and, moreover, that each component of the MetS may results in renal dysfunction." (PMID 34209146, 2021). "Given the relevance of renal dysfunction, inflammation, and the coagulation system in the development of cardiovascular diseases, we extended previous work on Cystatin C, CD14, SerpinG1, and SerpinF2 within circulating EVs to explore their possible associations with the CRS." (PMID 32648717, 2020). "Cystatin C, which is less influenced by sex, age and race, has been considered a novel sensitive marker for detecting renal dysfunction, and a combined creatinine-cystatin C equation has been suggested for classification of the estimated glomerular filtration rate (eGFR) instead of creatinine alone." (PMID 32306911, 2020). "Cystatin C in plasma was also associated with increased risk of renal dysfunction (OR of 2.89), whereas CD14 in plasma was not." (PMID 32648717, 2020). "Although Cystatin C was more potent marker for renal dysfunction, our study showed that the association for EV and plasma levels of Cystatin C with heart failure remained significant in patients with normal GFR levels." (PMID 32648717, 2020).
renal dysfunction (continued). "Serum cystatin C concentration was significantly higher in CLP operated groups both at 6–8 and 24 hrs when compared to shams (indicative of renal dysfunction), whereas cystatin C concentration was significantly lower at 24 hrs after surgery in the rapamycin treated group compared to CLP controls." (PMID 29348412, 2018). "Renal dysfunction which commonly occurs in patients with severe coronary artery disease and is partly reflected by elevated serum levels of cystatin C, adversely affects several components necessary for collateral growth through various regulatory mechanisms and gene expression." (PMID 29422093, 2018). "eGFRcys had a low diagnostic accuracy in stage 1 CKD at a cutoff value of 46.8 mL/min/1.73 m2, which is lower than that used clinically, suggesting that cystatin C might underestimate mild renal dysfunction." (PMID 28693441, 2017). "Similarly, when another renal dysfunction marker, cystatin C was measured, the magnitude of the urine cystatin C-to-creatinine ratio significantly increased in the HFD/STD group, and drug treatment groups showed significant decreases." (PMID 27097221, 2016). "Serum cystatin C (ScysC) may help predicting cardiovascular outcome not only through its ability to detect renal dysfunction but also through its potential connection to others factors that are directly related to cardiovascular diseases." (PMID 25495910, 2014). "Cystatin C,which has been proposed as a novel marker of renal dysfunction,is correlated with mortality in CAD, The purpose of the study was to evaluate whether cystatin C is a potential marker of asymptomatic CAD in MetS patients with normal kidney function." (PMID 22978689, 2012). "Taking into account the reduced availability of cystatin-C in routine laboratories and the cost, its usefulness as a prognostic factor should only be considered in patients with moderate degrees of renal dysfunction and it is advisable to continue using the classical eGFR formulas." (PMID 23240006, 2012). "Using cystatin C for eGFRcys, 20 patients (24%) could be classified with renal dysfunction." (PMID 39629062, 2024). "Therefore, serum cystatin C may be more sensitive than serum creatinine in detecting earlier stages of renal dysfunction among HCV-infected individuals." (PMID 36466932, 2022). "However, this study is the first indication that EV levels of CD14 and Cystatin C may be common markers for heart failure and renal dysfunction." (PMID 32648717, 2020). "Therefore cystatin C could be considered as a good candidate for the early detection of renal dysfunction in type 2 diabetic patients with normoalbuminuria." (PMID 28577020, 2017). "Likewise, renal dysfunction which commonly occurs in patients with severe coronary artery disease and is partly reflected by elevated serum levels of cystatin C, adversely affect several components necessary for collateral growth through various regulatory mechanisms and gene expression." (PMID 26402227, 2015). "Serum SSC5D levels were significantly correlated with indicators of renal dysfunction, such as eGFR, BUN, cystatin c, and creatinine." (PMID 37123263, 2023). "There were, however, differences observed between median renal function parameters (cystatin C, ACR and eGFR) between the two groups (p < 0.01), indicating that the patients with T2DM had more severe renal dysfunction." (PMID 35204128, 2022). "Median levels of Cystatin C and CD14 were the highest in patients with both heart failure and renal dysfunction in all three EV sub‐fractions." (PMID 32648717, 2020). "Similar results were shown in the Cardiovascular Health Study, which demonstrated cystatin C was correlated with CRP and fibrinogen in patients with mild to moderate renal dysfunction." (PMID 22978689, 2012). "Therefore, cystatin C could detect renal dysfunction one to two days before Cr." (PMID 17519026, 2007). "We did not evaluate microalbuminuria, cystatin C, or other biomarkers indicative of renal dysfunction." (PMID 40765549, 2025).
renal dysfunction (continued). "It has been postulated that serum cystatin C levels may be a more stable alternative to creatinine for glomerular filtration rate (GFR) and a potential new biomarker of renal dysfunction." (PMID 38779086, 2024). "Recent studies have shown that cystatin C does not overestimate renal function in cirrhosis as much as sCr and is a more accurate biomarker of renal dysfunction in patients with depleted liver function." (PMID 38139297, 2023). "We observed that serum creatinine and blood urea nitrogen levels in these patients correlated positively with plasma cystatin C levels, although none of the patients enrolled in our study presented with renal dysfunction." (PMID 37569647, 2023). "The relationship between a higher cystatin-C level and MVS may demonstrate the potential development of MVS-induced renal dysfunction." (PMID 35877566, 2022). "This study aimed to determine the association between cystatin C (CysC) and early cardiac functional or structural impairment in T2DM patients without renal dysfunction." (PMID 36104867, 2022). "Consequently, using formulas based on the level of cystatin C allows a more objective assessment of the category of GFR and detection of renal dysfunction in the early stages of development." (PMID 35928354, 2022). "In conclusion, we demonstrated that serum cystatin C was not superior to serum creatinine in the early detection of renal dysfunction in critically ill patients." (PMID 24783172, 2014). "Our data demonstrated that serum cystatin C is not superior to serum creatinine in the early detection of renal dysfunction in critically ill patients." (PMID 24783172, 2014). "They conclude that serum cystatin C was a better predictor than creatinine for the development of the mentioned events and identifies a state of “preclinical” renal dysfunction with cystatin C, which would not be detected by eGFRcreat alone." (PMID 24672725, 2014). "In other words, the false negative rates of serum creatinine and cystatin C in the detection of renal dysfunction were 56/60 (93.33%) and 48/60 (80%), respectively." (PMID 24783172, 2014). "The difference between false negative rates of serum creatinine (93.33%) and cystatin C (80%) in the detection of renal dysfunction was significant (P = 0.032)." (PMID 24783172, 2014). "It has been reported that urinary cystatin C concentration increases with renal tubular damage, independent of change in GFR, and that the cystatin C/creatinine ratio may be a suitable non-invasive method to detect renal dysfunction." (PMID 38732023, 2024). "Fourth, data on other indicators such as albumin/creatinine ratio and cystatin C were not routinely collected, which may lead to inaccuracy in determining renal dysfunction." (PMID 38435350, 2024). "This may be partly a consequence of the way to categorize cystatin C. As there is no standard threshold to define renal dysfunction based on cystatin C, renal dysfunction was just set based on the 75% quartile values of cystatin C without further confirmation." (PMID 29930507, 2018). "Unlike D-serine and creatinine, serum cystatin C, a marker for early detection of renal dysfunction, surged at 4 h and thereafter decreased gradually (Sham, 0.84±0.01 μg/ml; IRI 4, 1.63±0.08 μg/ml; IRI 8, 1.39±0.09 μg/ml; IRI 20, 1.19±0.05 μg/ml; IRI 40, 1.06±0.10 μg/ml)." (PMID 24489731, 2014). "In addition, other indicators of wRF, such as proteinuria/microalbuminuria, cystatin c, and free light chain measurements, which may represent more sensitive indicators of the early stages of renal dysfunction, were not included in this study." (PMID 38873847, 2024). "Cystatin C is a biomarker more independent of age or muscle mass compared to SCr, and it has been suggested that it might predict the risk of developing CKD at a mild, preclinical state of renal dysfunction." (PMID 33805740, 2021).
renal dysfunction (continued). "Notably, parameters such as Cystatin C and kidney injury molecule-1, which are additional indicators for post-PCI renal dysfunction, were not incorporated in this investigation." (PMID 39130830, 2024).
sarcopenia (105 papers, 2012 to 2026). Progressive decline in muscle mass due to aging which results in decreased functional capacity of muscles. "The results indicate that six predictive factors—body mass index, upper arm length, marital status, total cholesterol, cystatin C, and shoulder pain—are closely associated with the risk of sarcopenia in KOA patients." (PMID 40053240, 2025). "This study aimed to investigate the independent and joint associations of the serum creatinine-to-cystatin C ratio (sarcopenia index, SI) and PA with incident frailty in a nationally representative cohort of middle-aged and older Chinese adults." (PMID 41465771, 2025). "The sarcopenia index (SI), derived from serum creatinine (Cr)-to-cystatin C ratio, has demonstrated acceptable diagnostic accuracy in identifying individuals with sarcopenia [males: area under the curve (AUC) = 0.731; females: AUC = 0.711]." (PMID 40046757, 2025). "Multivariable Cox analysis was used to investigate the association of cystatin C, serum creatinine and sarcopenia index with cardiovascular and all-cause death." (PMID 39044229, 2024). "This study aimed to investigate the association of cystatin C, serum creatinine and sarcopenia index with cardiovascular and all-cause death in general population." (PMID 39044229, 2024). "Elevated cystatin C levels are associated with an increased risk of intertrochanteric fractures and have been linked to postoperative sarcopenia, which leads to more complications in patients with hip fractures." (PMID 39895817, 2024). "A recent study of 327 patients in China with resectable gastric cancer showed an association between a lower serum creatine/cystatin C ratio and the presence of imaging‐defined sarcopenia." (PMID 38646842, 2024). "The protein encoded by CST3 has been implicated as a biomarker for sarcopenia, as measured by the creatinine-to-cystatin C ratio." (PMID 38633108, 2024). "A low cystatin C-related index is associated with a high risk of sarcopenia and oral frailty from a medical perspective, whereas a high OFI-8 score recommends a precise evaluation of oral functions from a dental perspective." (PMID 37093792, 2023). "Some researchers combined creatinine and cystatin C as a novel index to evaluate muscle mass and a low serum creatinine level, most likely due to sarcopenia, is associated with a higher mortality rate." (PMID 36875836, 2023). "Since then, the creatinine/cystatin C ratio has been reported to be associated with sarcopenia and prognosis in various cancers." (PMID 37409249, 2023). "This study aimed to develop a simplified diagnostic tool for assessing sarcopenia and myosteatosis in gastrointestinal cancer patients, focusing on the creatinine to cystatin C ratio (CCR) as an evaluation marker." (PMID 37864250, 2023). "Future work examining renal function in the context of sarcopenia and dietary protein should consider other measures of renal function, such as Cystatin C, which are less associated with lean mass, to explore this relationship further." (PMID 36800504, 2023). "This study aimed to assess the utility of a baseline sarcopenia index (SI) based on serum creatinine (Cr)/cystatin C (CysC) as a prognostic marker for the risk of stroke recurrence and mortality in first-ever ischemic stroke older survivors (ISOS)." (PMID 37841730, 2023). "Creatinine/Cystatin C performed well not only in identifying non-sarcopenia cases, especially when based on FNIH diagnostic criteria, but also in revealing a positive association with higher risk of all-cause mortality." (PMID 36017221, 2022). "Creatinine and cystatin C are especially well known for being simple, economical and effective screening risk factors for sarcopenia." (PMID 36231280, 2022). "Using cystatin C, an endogenous filtration marker less influenced by muscle mass compared with creatinine, we found that sarcopenia was associated with increased serum cystatin C (i.e. decreased kidney function)." (PMID 33949807, 2021).